C3 (complement C3)
Diseases named in the same sentence as C3 in open-access papers (continued):
Sharing a sentence is not in itself a finding about the gene and the disease.
oral squamous cell carcinoma (2 papers, 2015 to 2019). "In the first approach, we have indeed found a higher expression of CFB and C3 proteins using a label-free pseudoSRM analysis of human saliva from Oral Squamous Cell Carcinoma (OSCC) patients in comparison with healthy individuals." (PMID 26540631, 2015).
otitis media (2 papers, 2020). Inflammation of the anatomical structures of the middle ear, which is most often caused by an infectious process. "In the ear, complement cleavage activation fragments of C3, C4, and Factor B have been detected in patients with otitis media with effusions." (PMID 32983170, 2020).
pericardial effusion (2 papers, 2024). Fluid collection within the pericardial sac, usually due to inflammation. "The patient exhibited significant hair loss, low complement levels (C3: 0.31 g/L; C4: 0.04 g/L), pleural and pericardial effusions, and renal involvement (serum creatinine: 101 μmol/L; 24-hour urinary total protein: 1.13 g/L)." (PMID 39081322, 2024).
placental insufficiency (2 papers, 2022 to 2023). Failure of the placenta to deliver an adequate supply of nutrients and oxygen to the fetus. "In an inducible rat model of placental insufficiency (reduced uterine placental perfusion through surgical manipulation), hypertensive rats had decreased circulating C3 and increased circulating C3a, showing that complement, specifically C3, activation had occurred." (PMID 36377667, 2023).
Pleuritis (2 papers, 2021 to 2026). Inflammation of the pleura. "Based on the presence of pleuritis, malar rash, reduction of C3 and C4 levels and positivity of antinuclear antibody (ANA) and anti-double stranded DNA (dsDNA), the diagnosis of juvenile SLE (JSLE) was performed." (PMID 34530845, 2021).
prediabetes (2 papers, 2018 to 2024). "The relationship between C3 and risk of DM in the general population supports the conclusion from other prospective studies demonstrating that elevated C3 levels are associated with an increased risk of IR, prediabetes and DM." (PMID 29895294, 2018). "In the prediabetes group, C3 concentration was reported as increased fold change with a fold change score of 1.13." (PMID 38739122, 2024).
primary open-angle glaucoma (2 papers, 2018 to 2022). "For instance, the complement factor 3 (C3) is upregulated in the aqueous humor of patients with primary open-angle glaucoma (POAG), particularly in those during disease progression." (PMID 36291747, 2022).
prostatitis (2 papers, 2017 to 2022). An infectious or non-infectious inflammatory process affecting the prostate gland. "Studies have confirmed that inflammation and immune factors (IgE, complement C4, complement C3, CRP, ASO, and RF) and hormone elements (Osteoc, FSH, testosterone, and insulin) are significantly related to the occurrence of prostatitis." (PMID 36071874, 2022). "Complement C4, complement C3, CRP, and IL-6 are commonly used in clinic to evaluate inflammation, but no causal relationship between C3, CRP, IL-6, and prostatitis was found in this study." (PMID 36071874, 2022). "Therefore, our research group conducted linkage disequilibrium (LDSC) analysis on the relationship between prostatitis and clinical in the early stage and found that complement C4 and C3 have significant correlation with prostatitis, but it is not clear whether there is a causal relationship." (PMID 36071874, 2022).
pulmonary TB (2 papers, 2014 to 2021). "MHC complement genes C2, C4, and factor B (FB), and C3 have been studied in an Indian population showing increased frequencies of complete C4A deficiency, BF*FA and C3*F in patients with pulmonary tuberculosis compared with healthy individuals." (PMID 24638111, 2014).
rapidly progressive glomerulonephritis (2 papers, 2023 to 2025). Inflammation of the glomeruli that is characterized by a rapid loss in renal function with glomerular crescent formation observed on biopsy; it is often seen in patients with concomitant autoimmune disease, like Goodpasture's syndrome or systemic lupus erythematosus. "With the clinical suspect of an infection-triggered rapidly progressive glomerulonephritis (RPGN) superimposed on SRNS, we performed a second kidney biopsy which confirmed a proliferative GN with few crescents, as well as IgG and C3 deposition along the glomerular basement membrane." (PMID 41141520, 2025).
Recessive Stargardt disease (2 papers, 2023 to 2025). "Ng ESY and co-authors also reported that the activation of C3 complement factor and the insertion of MAC complex on the surface of retinal pigment epithelial (RPE) cells in patients suffering from Recessive Stargardt disease (STGD1) can increase their death rate and worsen the existing retinopathy." (PMID 39485618, 2025). "In addition to what has been mentioned, in Stargardt disease, lipofuscin-accumulated RPE cells display increased activity of C3 complement, and as there is a negative correlation between C3 and CD46 levels, the inhibition of the complement cascade decreases." (PMID 37600916, 2023).
retinitis pigmentosa (2 papers, 2022 to 2023). Retinitis pigmentosa (RP) is an inherited retinal dystrophy leading to progressive loss of the photoreceptors and retinal pigment epithelium and resulting in blindness usually after several decades. "Similar paradoxical findings for the roles of neuroinflammatory C3 + neuroglia cells have been reported in retinitis pigmentosa, specifically C3 + microglia." (PMID 36915214, 2023).
Right ventricular hypertrophy (2 papers, 2023 to 2024). In this case the right ventricle is more muscular than normal, causing a characteristic boot-shaped (coeur-en-sabot) appearance as seen on anterior- posterior chest x-rays. "Pharmacological inhibition of complement C3 cleavage (CP40-KK) could ameliorate MCT-induced NLRP3 inflammasome activity, pulmonary vascular remodeling, and right ventricular hypertrophy." (PMID 38365806, 2024).
sarcopenia (2 papers, 2024). Progressive decline in muscle mass due to aging which results in decreased functional capacity of muscles. "Additionally, the DJ-1-knockout model has a reduced level of Complement C3, another biomarker associated with sarcopenia." (PMID 39765837, 2024). "The present study seeks to determine the relationship between serum complement C3 levels and body composition and sarcopenia-related status in community-dwelling older adults." (PMID 38279167, 2024).
scrapie (2 papers, 2015 to 2021). A fatal disease of the nervous system in sheep and goats, characterized by pruritus, debility, and locomotor incoordination. "Reduced levels of C3 mRNA were also observed in brain tissue from scrapie-infected C/EBPD(-/-) mice." (PMID 26230261, 2015). "Likewise, C3 transcript levels showed also the most pronounced differences in comparisons of mRNA levels in scrapie-infected C/EBPD(+/+) and C/EBPD(-/-) mouse brains." (PMID 26230261, 2015). "Transcript levels of C3 and Saa3 were significantly lower in brain tissue from APP/PS1 x C/EBPD(-/-) mice and scrapie-infected C/EBPD(-/-) mice compared to the respective controls." (PMID 26230261, 2015). "In addition, C1q upregulation, C3 upregulation and colocalization with neurons, and MAC deposition on neurons were observed in infected human brain as well as in scrapie model in mice, suggesting the activation of the classical and terminal pathways." (PMID 34408631, 2021).
skin cancer (2 papers, 2021 to 2025). "The absence of C3 strongly protected against skin cancer development in the inflammation-driven DMBA-TPA model of cSCC but not in the absence of the inflammatory stimulus." (PMID 32682912, 2021).
squamous cell carcinoma of the cervix (2 papers, 2021 to 2024). "A1BG together with Complement C3 was shown to be overexpressed in serum samples from patients with squamous cell carcinoma of the cervix and grade III cervical intraepithelial cancer, compared to healthy control women." (PMID 34885011, 2021). "In patients with squamous cervical cancer, APOA1 overexpression can reduce the sensitivity of cervical squamous cells to carboplatin by regulating the expression of STAT1, CD81, C3, and TOP2A." (PMID 38212711, 2024).
Still’s disease (2 papers, 2024 to 2025). "On the other hand, a patient identified with Still’s disease had elevated levels of C3, anti-SSA antibodies, and anti-Ro-52 antibodies." (PMID 38959275, 2024).
teratoma (2 papers, 2017 to 2024). A non-seminomatous germ cell tumor characterized by the presence of various tissues which correspond to the different germinal layers (endoderm, mesoderm, and ectoderm). "HM-KO teratomas in NK cell-deficient C3−/− mice and HM-KO NK teratomas in C3−/− mice also grew larger than HM-KO comp teratomas in NK cell-deficient B6 mice." (PMID 38215755, 2024). "Consistent with HM-KO NK and comp teratomas, both HM-KO teratomas in NK cell-deficient C3−/− mice and HM-KO NK teratomas in C3−/− mice persisted for at least 12 weeks after transplant." (PMID 38215755, 2024). "Given teratomas still plateau in C3−/− mice, ablation of the complement pathways is not limiting teratoma size." (PMID 38215755, 2024).
thymoma (2 papers, 2022 to 2024). A neoplasm arising from the epithelial cells of the thymus. "Analogous to simple SLE, a variety of antibodies can be detected in the serum of patients with thymoma combined with SLE, and there may be increased IgG and IgM, and decreased C3 and C4." (PMID 36626535, 2022).
thyroid (2 papers, 2022 to 2025). "Notably, this study is the first to identify C3 eQTLs as a central regulatory nexus bridging genetic susceptibility and complement-driven thyroid irAEs." (PMID 41221294, 2025).
viral myocarditis (2 papers, 2022 to 2025). Myocarditis that is caused by an infection with a viral agent. "Ultimately, four overlapping features, namely, B2M, C3, CFB, and CASP12, were selected as potential biomarkers for viral myocarditis using both algorithms." (PMID 40230577, 2025).
Waldenström macroglobulinemia (2 papers, 2016 to 2022). "According to immunologic data, only 3 patients had low blood complement C3, C4, and CH50 levels; all these patients were diagnosed with Waldenström’s macroglobulinemia." (PMID 26892336, 2016).
Acute hepatitis (1 paper, 2024). Acute hepatic injury resulting from inflammation typically accompanied by increased serum alanine transaminase activity. "Results for antinuclear antibody, acute hepatitis panel, double-stranded deoxyribonucleic acid, rheumatoid factor, complement levels (C3 and C4), and antineutrophil cytoplasmic antibody profile were all normal." (PMID 38960929, 2024). "Other tests, including serum immunoglobulins (IgA, IgG, and IgM), antinuclear antibody, acute hepatitis panel, double-stranded deoxyribonucleic acid, rheumatoid factor, complement levels (C3 and C4), and antineutrophil cytoplasmic antibody profile, all yielded negative results." (PMID 38960929, 2024).
adult-onset Still disease (1 paper, 2023). A rare inflammatory multisystem disorder characterized clinically by fever of unknown origin, arthralgia or arthritis, hyperleucocytosis, and typical skin rash. "Clinically, low C3/C4, possibly reflecting complement consumption, has been described in 2 patients with SJIA-MAS and 1 patients with adult-onset Still’s disease MAS." (PMID 37733441, 2023).
afibrinogenemia (1 paper, 2010). "For example the expression of the C3 protein, an acylation stimulating protein involved in necrosis and afibrinogenemia (blood disorders), has been shown to be affected by PA in rats." (PMID 20502671, 2010).
anterior uveitis (1 paper, 2023). Inflammation of the iris and anterior chamber of the eye. "In contrast to our expectation, we noticed a downregulation of C3 and CFH expression in peripheral leukocytes of patients with anterior uveitis as compared to controls." (PMID 38187376, 2023).
anticoagulant (1 paper, 2025). "These tests included the lupus anticoagulant, anticardiolipin IgG, IgM, C3, C4, ANA, anti-dsDNA, ADAMST13, and RF, all of which were negative." (PMID 40364871, 2025).
aortic atherosclerosis (1 paper, 2022). A atherosclerosis that involves the aorta. "Of interest, C3 is an MSRN protein and aortic atherosclerosis is worse in aortas from C3-deficient mice than in controls." (PMID 36362037, 2022).
Apathy (1 paper, 2025). Apathy is a quantitative reduction of interest, motivation and the initiation and persistence of goal-directed behavior, where often the accompanying emotions, thoughts, and social interactions are also diminished. "Composite apathy scores were strongly and positively correlated with mRNA fold changes for all examined genes: Tyrobp, Trem2, C1qa, C1qb, C1qc, C3, C3ar1, and Cd33 (p < 0.0001)." (PMID 41377997, 2025). "C3 (r = 0.6907) and its receptor C3ar1 (r = 0.8596), key components of the C3 signaling pathway, were positively correlated with apathy." (PMID 41377997, 2025). "The reduction in C3 and C3ar expression following combination drug treatment further supports our hypothesis and highlights C3ar as a potential therapeutic target for apathy in AD." (PMID 41377997, 2025).
aspergillosis (1 paper, 2022). Aspergillosis is an infection, growth, or allergic response caused by the Aspergillus fungus. "We also examined if C3 deficiency on different genetic backgrounds alters the susceptibility to aspergillosis, particularly on Th1-biased C57BL/6 and Th2-biased BALB/c mice." (PMID 36211424, 2022).
atopic dermatitis (1 paper, 2025). "Human evidence suggests that serum C3 levels decrease by ≈27% after 10 HBOT sessions in patients with severe atopic dermatitis." (PMID 41312352, 2025).
autoimmune diseases of the nervous system (1 paper, 2024). "Studies also report that changes in C3 complement are associated with the development and progression of autoimmune diseases of the nervous system." (PMID 39087011, 2024).
B-cell NHL (1 paper, 2014). "The acute phase protein, SAA has been shown to be overexpressed in B-cell NHL associated with SIV infection in monkeys, and complement components (C3 and CR2) may be involved in lymphomagenesis and/or complement activation." (PMID 24922518, 2014).
benign papilloma (1 paper, 2018). "Chemically induced mouse cSCC and 8 cSCC cell lines showed significant upregulation of C3 and CFB (complement factor B) gene and protein expression compared to benign papilloma and normal human epidermal keratinocytes." (PMID 29423024, 2018).
bone metastasis (1 paper, 2021). Transfer of a neoplasm from its primary site to bones. "Among these genes, NCAM1 expressed higher in bone metastasis group, while CXCL10 and C3 expressed lower in bone metastasis group." (PMID 33859877, 2021).
C. perfringens infection (1 paper, 2025). "Moreover, the findings underscore a coordinated effort of the host to mitigate the C. perfringens infection via activating immune (a.o., C3, CFH, MASP2, MBL2) and acute phase (CP, ORM, TF, ExFAB) related proteins." (PMID 40275387, 2025).
cerebral malaria (1 paper, 2008). A sequestration of Plasmodium falciparum in the brain, which can cause coma and/or seizures. "The current study was conducted to analyze complement factors C1q, C3 and C5 – catalyzing crucial steps in the complement cascade – in the brains and sera of mice infected with Plasmodium berghei ANKA – a well-established model of cerebral malaria." (PMID 18847493, 2008).
cholestasis (1 paper, 2022). Impairment of the bile flow caused by obstruction within the liver, or outside the liver in the bile duct system. "Previously, some authors discovered that complement may not be activated in PBC and that an increase in serum C3 levels is associated with cholestasis." (PMID 35884999, 2022).
Chronic constipation (1 paper, 2023). Constipation for longer than three months with fewer than 3 bowel movements per week, straining, lumpy or hard stools, and a sensation of anorectal obstruction or incomplete defecation. "Therefore, it can be seen that AEtLP has similar therapeutic effects in improving chronic constipation induced either by Lop injection or C3 deficiency." (PMID 37958740, 2023).
chronic graft versus host disease (1 paper, 2018). Chronic graft versus host disease (GVHD) is a complication that can occur after a stem cell or bone marrow transplant in which the newly transplanted donor cells attack the transplant recipient's body. "Adoptive transfer of CD8+CD103+ iTreg but not control cells to chronic graft-versus-host disease with a typical lupus syndrome showed decreased levels of autoantibodies and proteinuria, reduced renal pathological lesions, lowered renal deposition of IgG/C3, and improved survival." (PMID 29441062, 2018).
colorectal tumor (1 paper, 2021). "In a mouse model of colorectal tumor transplantation, complement inhibition and complement depletion were used to reduce the plasma levels C3 and it was found that a reduction of C3 levels inhibited tumor growth, while tumor progression was resumed upon replenishment of C3." (PMID 34722636, 2021).
complement over activation (1 paper, 2020). "Our results suggest that acadesine suppresses TNF-α induced C3, likely through an AMPK-independent pathway, and could have potential use in complement over activation diseases." (PMID 33362238, 2020).
congenital cataracts (1 paper, 2023). "Some studies have shown that the amount of complement C3 in the peripheral blood of sick patients with congenital cataracts is dramatically decreased, and the reduction of complement C3 is a risk factor for congenital cataracts." (PMID 36586009, 2023). "C1q ultimately leads to the conditioning and phagocytosis of C3 by complement receptor macrophages, so the amount of complement C3 is a risk factor for congenital cataracts and indirectly implies the inducing effect of C1q on the occurrence and development of congenital cataracts." (PMID 36586009, 2023).
coronary artery calcification (1 paper, 2023). Calcification of the coronary artery, used as a measure of coronary atherosclerosis, a risk factor for myocardial infarction. "In a PCOS population, complement C3 was associated with coronary artery calcification." (PMID 36980195, 2023).
dental abscess (1 paper, 2022). "Kettering and Torabinejad (1984), looking at the effect of dental abscess on the levels of C3, found that serum levels of C3 were higher in patients with acute apical conditions when compared to controls." (PMID 35888650, 2022).
diabetic eye disease (1 paper, 2023). A group of disorders affecting the eye in patients with diabetes mellitus. "In systemic investigation of DR patients, the level of C3, C3-activated fragment C3bα’, and CFH are upregulated in the vitreous of PDR patients, and a strong correlation exists between aqueous and vitreous complement levels in diabetic eye disease." (PMID 37569464, 2023).
discoid lupus erythematosus (1 paper, 2025). A chronic, autoimmune skin condition that manifests with a red, scaling rash, most often found on the face, ears, and scalp; these lesions often lead to permanent scarring and dyspigmentation. "All patients exhibited mucocutaneous involvement, discoid lupus erythematosus, inflammatory polyarthritis, normal serum complements C3 and C4, coarse-speckled Antinuclear antibody positivity and antibodies to ribonucleoprotein." (PMID 40556690, 2025).
Down syndrome (1 paper, 2011). "In conclusion, there is substantial evidence showing C1q, C4 and C3 strongly associated with fibrillar plaques in human AD brain and Down's Syndrome with AD even in early stages of the disease correlating with the appearance of fibrillar amyloid." (PMID 21235806, 2011).
edema (1 paper, 2017). An abnormal accumulation of fluid beneath the skin, or in one or more cavities of the body. "This study demonstrates that tPA promotes C3 cleavage through an extrinsic pathway, and the C3a anaphylatoxin thus generated promotes post-ischemic brain hemorrhage and cerebral edema." (PMID 28700732, 2017).